CREBZF (CREB/ATF bZIP transcription factor)
Diseases named in the same sentence as CREBZF in open-access papers:
CREBZF is named in the same sentence as 27 diseases in open-access papers, as found by Europe PMC text mining. Sharing a sentence is not in itself a finding about the gene and the disease. The quoted sentences say what the papers report.
breast carcinoma (2 papers, 2022 to 2023). "Herein, this study aimed at disclosing the specific function and the underlying mechanism of lncRNA MBNL1/miR-423-5p/CREBZF axis in promoting breast cancer progression, so as to provide a potential novel biomarker for predicating the survival of breast cancer patients." (PMID 35094653, 2022). "In summary, our results indicate that circPAPD4 overexpression inhibits breast cancer progression by modulating the miR-1269a/CREBZF axis." (PMID 37264406, 2023). "To verify the therapeutic feasibility of CREBZF-mRNA-NPs in breast cancer xenograft model, we systemically injected CREBZF-mRNA-NPs through tail vein in nude mice bearing CREBZF-null MCF-7 xenograft tumors every three days for seven injections cycles." (PMID 37264406, 2023). "As a result, our work illustrated the tumor suppressor role of MBNL1-AS1 in breast cancer via upregulating miR-423-5p-targeted CREBZF." (PMID 35094653, 2022). "In summary, our work illustrated the tumor suppressor role of MBNL1-AS1 in breast cancer via the upregulation of miR-423-5p-targeted CREBZF." (PMID 35094653, 2022). "It was apparent to see declining CREBZF mRNA level in 60 pairs of breast cancer patient tissues compared with that in normal tissues." (PMID 35094653, 2022). "To further investigate whether circPAPD4 inhibits breast cancer progression through CREBZF, we silenced CREBZF expression using shRNA (sh-CREBZF) in MCF-7 and SKBR-3 cells." (PMID 37264406, 2023). "Thereby, the evidence points that a complete understanding of MBNL1-AS1/miR-423-5p/CREBZF axis in regulating breast cancer development is required, and that it could be seen as a biomarker in predicating survival of breast cancer patients." (PMID 35094653, 2022). "Thereby, the evidence indicates the complete understanding of the role of MBNL1-AS1/miR-423-5p/CREBZF axis in the regulation of breast cancer development, which could be used as a biomarker for predicating survival among breast cancer patients." (PMID 35094653, 2022). "Also, the associated regulation network partly explained that MBNL1-AS1 exerted its function by regulating miR-423-5p/CREBZF axis, which can be a novel biomarker of breast cancer." (PMID 35094653, 2022). "Our findings firstly illustrated that circPAPD4/miR-1269a/CREBZF/STAT3/ADAR1 positive feedback loop mediated BC progression, and delivering CREBZF mRNA nanoparticles suppressed BC progression in vitro and in vivo, which might provide novel insights into therapeutic strategies for breast cancer." (PMID 37264406, 2023). "However, the specific function of CREBZF in carcinomas, especially in breast cancer, has not been investigated." (PMID 35094653, 2022).
fatty liver disease (2 papers, 2023 to 2024). A reversible condition wherein large vacuoles of triglyceride fat accumulate in liver cells via the process of steatosis. "Moreover, the knockdown of CREBZF resulted in hepatic steatosis." (PMID 36769229, 2023). "Our findings showing CREBZF as a NF‐κB coregulator under overnutrition, coupling with the effects of CREBZF on exacerbated hepatic steatosis and NASH, suggest that targeting CREBZF may represent general benefits in treating metabolic diseases." (PMID 38286660, 2024). "This study indicates that CREBZF can also act as a negative mediator in fatty liver disease." (PMID 36769229, 2023).
Obesity (2 papers, 2024). Accumulation of substantial excess body fat. "Next, we addressed the role of macrophage CREBZF in obesity‐associated inflammation induced by HFHS diet." (PMID 38286660, 2024). "Gain‐ and loss‐of‐function approaches demonstrate that CREBZF‐mediated regulation of the NF‐κB signaling couples inflammatory signals to metabolic homeostasis in obesity." (PMID 38286660, 2024). "CREBZF has been associated with innate immune responses, obesity, and energy metabolism, as well as inhibiting liver regeneration." (PMID 38632526, 2024). "Furthermore, obesity‐associated proinflammatory stimuli like palmitic acid or LPS induced CREBZF in macrophages." (PMID 38286660, 2024). "To test the efficacies of pharmacological inhibition of CREBZF in the attenuation of obesity‐associated inflammation and insulin resistance, we adapted a luciferase assay to a high‐throughput screening (HTS) strategy for identifying potential compounds that repress the transcription of CREBZF." (PMID 38286660, 2024). "We identified bromocriptine in a blind screen for CREBZF inhibitors and showed that it partially prevents obesity‐related inflammatory and metabolic disorders by inhibiting CREBZF." (PMID 38286660, 2024).
osteosarcoma (2 papers, 2023). A usually aggressive malignant bone-forming mesenchymal neoplasm, predominantly affecting adolescents and young adults. "Recent studies reported that the dysregulation of CREBZF regulated the development of several cancers including melanoma, medulloblastoma, gastric adenocarcinoma, and osteosarcoma, by affecting tumor cell proliferation and apoptosis." (PMID 37264406, 2023). "Previous studies have shown that CREBZF is present in both the nucleus and cytoplasm of osteosarcoma cells and human livers." (PMID 37264406, 2023).
viral infection (2 papers, 2020 to 2022). "FAdVcirc_013009 and FAdVcirc_011337 target the gga-miR-7475-5p, which negatively correlated with CREBZF and LFNG during FAdV-4 infection, and these genes were all associated with the host cell response to viral infection." (PMID 35722302, 2022). "Furthermore, gga-miR-7475-5p was negatively correlated with CREBZF and LFNG during FAdV-4 infection at 120 min; studies showed that these genes were all associated with the host cell response to viral infection." (PMID 32508763, 2020).
adenoma (1 paper, 2020). A neoplasm arising from the epithelium. "However, we did not carry out a large-scale study of gastric adenoma/dysplasia and adenoma cell lines to identify miRNAs with CREBZF involved in GC progression, which remains one of the limitations of this study." (PMID 32218690, 2020).
dysplasia (1 paper, 2020). A usually neoplastic transformation of the cell, associated with altered architectural tissue patterns. "Our data showed that CREBZF is a target gene of hsa-miR-421/hsa-miR-29b-1-5p and might play an important role in the development of GC from gastric adenoma/dysplasia." (PMID 32218690, 2020).
gastric adenocarcinoma (1 paper, 2020). "In our previous study, we identified three miRNAs (hsa-miR-421, hsa-miR-29b-1-5p, and hsa-miR-27b-5p) with two mRNAs (FBXO11 and CREBZF) that might play an important role in the development of gastric adenocarcinoma (GAC) from premalignant adenomas." (PMID 32218690, 2020).
gastric adenoma (1 paper, 2020). A neoplastic polyp that arises from the stomach. "Moreover, why CREBZF is downregulated in gastric adenoma/dysplasia is an interesting phenomenon that requires further investigation." (PMID 32218690, 2020).
gastric cancer (1 paper, 2020). A primary or metastatic malignant neoplasm involving the stomach. "We observed lower expression of CREBZF with increasing miRNAs in the MKN-74 gastric cancer cells compared to that in SNU-NCC-19." (PMID 32218690, 2020). "We postulated that CREBZF and the miRNAs were potentially novel tumor biomarker for the progression of GC in low-/high-grade dysplasia and early gastric cancer patients." (PMID 32218690, 2020). "Next, the role of CREBZF in MKN-74 gastric cancer cells was investigated via cell viability and migration assays by miRNA/anti-miRNA modulation." (PMID 32218690, 2020). "Considering that targets can modulate in GC, we analyzed the CREBZF expression in gastric cancer cell lines by RT-PCR and western blot analysis." (PMID 32218690, 2020). "This study suggests that increased CREBZF by hsa-miR-421/hsa-miR-29b-1-5p inhibition may be important to prevent the progression of gastric cancer in its early stage." (PMID 32218690, 2020). "We investigated the roles of CREBZF and miRNAs as potential biomarkers for the progression of gastric cancer (GC) in low-/high-grade dysplasia and early gastric cancer patients using immunohistochemical staining and miRNA in situ hybridization." (PMID 32218690, 2020).
Glucose intolerance (1 paper, 2024). Glucose intolerance (GI) can be defined as dysglycemia that comprises both prediabetes and diabetes. "In the absence of neutrophils, CREBZF deficiency in myeloid cells remains the effects of attenuated HFHS diet‐induced glucose intolerance, insulin resistance, and inflammation." (PMID 38286660, 2024).
Hyperglycemia (1 paper, 2024). An increased concentration of glucose in the blood. "CREBZF deficiency in macrophages, not in neutrophils, attenuates macrophage infiltration in adipose, proinflammatory activation, and hyperglycemia in diet‐induced insulin‐resistant mice." (PMID 38286660, 2024). "Pharmacological and genetic inhibition of CREBZF attenuates hyperglycemia and type 2 diabetes." (PMID 38286660, 2024). "Moreover, CREBZF deficiency decreased the proinflammatory activities of ATM, which preceded the improvement of hyperglycemia and insulin resistance." (PMID 38286660, 2024). "CREBZF is induced by the overnutrition status in humans and mice, and the pharmacological and genetic inhibition of CREBZF attenuates symptoms of T2DM further solidifying the role of CREBZF in regulating hyperglycemia." (PMID 38286660, 2024).
Insulin resistance (1 paper, 2024). Increased resistance towards insulin, that is, diminished effectiveness of insulin in reducing blood glucose levels. "Collectively, these findings demonstrate that CREBZF is dynamically regulated in response to inflammatory stimuli, and hyper‐activation of CREBZF in macrophages contributes to systemic insulin resistance and type 2 diabetes." (PMID 38286660, 2024). "Next, we explored how CREBZF regulates macrophages to influence metabolic homeostasis and insulin resistance." (PMID 38286660, 2024). "In summary, the current study demonstrates a novel mechanism of the CREBZF‐NF‐κB axis in the macrophage regulating inflammation and insulin resistance." (PMID 38286660, 2024). "This study demonstrates that CREBZF acts as a novel regulator in macrophage‐mediated inflammation and insulin resistance." (PMID 38286660, 2024). "The present study demonstrates that overnutrition‐induced CREBZF links adipose tissue macrophage (ATM) proinflammatory activation to insulin resistance." (PMID 38286660, 2024). "Moreover, we demonstrate that pharmacological inhibition of CREBZF attenuates inflammation and insulin resistance in obese mice." (PMID 38286660, 2024). "This study identifies a previously unknown role of CREBZF coupling ATM activation to systemic insulin resistance and type 2 diabetes." (PMID 38286660, 2024). "This study characterizes a previously unknown function for CREBZF in regulating macrophage‐mediated inflammation and insulin resistance." (PMID 38286660, 2024). "Notably, specific depletion of neutrophils did not abolish the augmentative effects of myeloid CREBZF deficiency on attenuating insulin resistance." (PMID 38286660, 2024). "Furthermore, CREBZF is highly expressed in ATM of obese humans and mice, which is positively correlated with proinflammatory genes and insulin resistance in humans." (PMID 38286660, 2024). "Given the clues that CREBZF regulates insulin resistance via the crosstalk between ATM and adipocytes, we screened a small molecule compound bromocriptine mesylate, which inhibits CREBZF to suppress inflammation and ameliorates insulin resistance." (PMID 38286660, 2024).
ovarian carcinoma (1 paper, 2023). A malignant neoplasm originating from the surface ovarian epithelium. "The abnormal expression of CREBZF is closely correlated to cancer progression and prognosis; for example, high CREBZF expression predicts poor OS and/or progression-free survival in patient with ovarian cancer, and it is considered as a biomarker for the pathological progression of GC." (PMID 37771430, 2023).
overnutrition (1 paper, 2024). An imbalanced nutritional status resulting from excessive intake of nutrients. "Our findings show that CREBZF functions as a coregulator to promote NF‐κB transcriptional activity, which underlies chronic low‐grade inflammation associated with overnutrition." (PMID 38286660, 2024). "Additionally, the findings of CREBZF on regulating NF‐κB signaling represent an unknown mechanism that underlies chronic low‐grade inflammation associated with overnutrition." (PMID 38286660, 2024). "In response to overnutrition, CREBZF in macrophages is activated and aggravates inflammation leading to impaired insulin signaling." (PMID 38286660, 2024). "This current study identifies that overnutrition and inflammation increase the expression of CREBZF." (PMID 38286660, 2024).
Type 2 Diabetes (1 paper, 2024). "One of the most important findings is the therapeutic potential of targeting CREBZF in type 2 diabetes (T2DM)." (PMID 38286660, 2024). "The transcriptional coregulator CREBZF is a key factor in hepatic metabolism, yet its role in modulating adipose tissue inflammation and type 2 diabetes remains elusive." (PMID 38286660, 2024).
tumor (6 papers, 2011 to 2024). "CREBZF-mRNA-NPs considerably suppressed tumor growth, while both control groups (treatment with PBS and control NPs) showed rapid tumor growth." (PMID 37264406, 2023). "Collectively, these results indicate that CREBZF-mRNA-NPs effectively suppressed tumor progression with negligible side effects." (PMID 37264406, 2023). "Notable, genes involved in TGF-β signalling (SOS1, SOS2, SMAD5, LTBP3, TGFBR2, IRF7 and CREBZF) were found to be significantly (P<0.01) downregulated in the VEGFA165 tumours." (PMID 22045186, 2011). "Collectively, these findings indicate that CREBZF-mRNA-NPs could effectively deliver CREBZF mRNA to tumor cells, reduce proliferation, and promote apoptosis in CREBZF-null MCF-7 cells." (PMID 37264406, 2023). "In conclusion, CREBZF knockdown could reverse the suppressive effect on MCF-7 cell proliferation, migration, and invasion brought about by miR-424-5p inhibitor and CREBZF could serve as a tumor suppressor." (PMID 35094653, 2022). "However, there have been few reports regarding the tumor suppressive role of CREBZF and we were the first to describe the important role of CREBZF and microRNAs (miRNA) in GC development from premalignant adenomas." (PMID 32218690, 2020). "In addition, compared to either PBS or control NPs, immunofluorescence and FISH analysis of tumor sections revealed that CREBZF-mRNA-NPs promoted CREBZF and circPAPD4 expression, inhibited ADAR1 expression, and significantly discouraged proliferation while encouraging apoptosis of tumor cells." (PMID 37264406, 2023).
cancer (4 papers, 2020 to 2023). A tumor composed of atypical neoplastic, often pleomorphic cells that invade other tissues. "The other isoform of SMILE, CREBZF/Zhangfei, is known to be involved in reproduction, cancer, apoptosis, and other cellular functions." (PMID 36769229, 2023). "The migration and invasion capacities of cancer cells were strengthened because of declining the CREBZF level in si-CREBZF + miR-423-5p inhibitor group compared with that in the miR-423-5p inhibitor group." (PMID 35094653, 2022). "Through several in vitro experiments, CREBZF knockdown was found to impair the deterioration of cancer cell growth mediated by low miR-423-5p expression." (PMID 35094653, 2022). "CREBZF/SMILE is also reported to play a role in cancer cells and apoptosis." (PMID 36769229, 2023). "Accordingly, CREBZF knockdown could impair the hindrance of cancer cell growth mediated by low miR-423-5p expression." (PMID 35094653, 2022). "CREBZF knockdown could impair the deterioration of cancer cell growth mediated by low miR-423-5p expression." (PMID 35094653, 2022). "Considering that targets can modulate in GC, we investigated the differential expression of two targets (CREBZF and FBXO11) with three miRNAs (hsa-miR-421, hsa-miR-29b-1-5p, hsa-miR-27b-5p) using two different cancer cell lines (SNU-NCC-9 and MKN74)." (PMID 32218690, 2020).
adenocarcinoma (1 paper, 2020). A common cancer characterized by the presence of malignant glandular cells. "Consistent with our previous findings (microarray and qPCR), the expression of CREBZF was found to be lower in invasive neoplastic glands of adenocarcinoma tissues than in normal pair tissues by immunohistochemical staining." (PMID 32218690, 2020).
metabolic disorders (1 paper, 2024). "Taken together, the in vivo evidence suggests that CREBZF is required for the beneficial effects of bromocriptine on anti‐inflammatory phenotype and improved insulin sensitivity in mice, and pharmacological inhibition of CREBZF may have potential therapeutic effects on metabolic disorders." (PMID 38286660, 2024).
CREBZF also shares sentences with these, for which no sentence is quoted: adrenal hypoplasia (1 paper); Denys-Drash syndrome (1); glucocorticoid deficiency (1); Hepatic steatosis (1); infection (1); medulloblastoma (1); pancreatic cancer (1).